TNP1 (transition protein 1)
Description:
Plays a key role in the replacement of histones to protamine in the elongating spermatids of mammals. In condensing spermatids, loaded onto the nucleosomes, where it promotes the recruitment and processing of protamines, which are responsible for histone eviction.
Synonyms: TP1
Tractability: No criterion of Open Targets' tractability assessment is met for any kind of drug.
Gene: Protein-coding gene on chromosome 2 (216,859,458 to 216,860,064, reverse strand). Ensembl gene ENSG00000118245.
Subcellular location: Nucleus; Chromosome
Gene Ontology:
Molecular function: DNA binding; protein binding
Biological process: chromatin remodeling; flagellated sperm motility; heterochromatin formation; negative regulation of DNA-templated transcription; nucleosome disassembly; sexual reproduction; single strand break repair; spermatid development; spermatid nucleus elongation; positive regulation of protein processing; sperm DNA condensation; sperm DNA decondensation; spermatid nucleus differentiation; spermatogenesis
Cellular component: nucleosome; chromosome; male germ cell nucleus; nucleus
Genetic constraint (gnomAD): Loss-of-function variants: 1 observed, 6.13 expected, observed/expected ratio (o/e) 0.16, 90% interval 0.057 to 0.77. That is too few expected variants to judge how well the gene tolerates losing a copy. Missense variants: 71 observed, 79.3 expected, observed/expected ratio (o/e) 0.9, 90% interval 0.74 to 1.09. Synonymous variants: 22 observed, 26.74 expected, observed/expected ratio (o/e) 0.82, 90% interval 0.59 to 1.17.
Homologues: Orthologues: macaque TNP1 (100% identical), chimpanzee TNP1 (98% identical), rabbit TNP1 (93% identical), dog TNP1 (91% identical), pig TNP1 (91% identical), mouse Tnp1 (87% identical), rat Tnp1 (87% identical), guinea pig TNP1 (82% identical).
Diseases named in the same sentence as TNP1 in open-access papers:
TNP1 is named in the same sentence as 20 diseases in open-access papers, as found by Europe PMC text mining. Sharing a sentence is not in itself a finding about the gene and the disease. The quoted sentences say what the papers report.
Infertility (9 papers, 2014 to 2024). "The aim of present study was to investigate the association of TNP1 mutations with varicocele-associated infertility patients." (PMID 24976820, 2014). "Materials and Methods: Analysis of association between TNP1 gene mutation and varicocele phenotype was performed using PCR and Single-Stranded Conformational Polymorphism technique and DNA sequencing in 82 varicocele infertile men and 80 control subjects." (PMID 24976820, 2014). "Finally, two IVF-DMRs associated with infertility (TNP1 and C9orf3) were targeted for validation." (PMID 28340599, 2017). "We pursued validation of the differential methylation signals at the top associated DMR (located ~3 kb upstream of TNP1) and at the third-ranked DMR (located in C9orf3), both in or near genes previously linked to infertility." (PMID 28340599, 2017). "There is a significant overexpression of miR27a in infertile men with nonobstructive azoospermia, which target several genes, including H3K9 demethylase that regulates transcriptional suppression of Tnp1/Prm1, resulting in infertility in animal models and humans." (PMID 36899892, 2023). "Without the function of KDM3A in round spermatids, excessive methylation would lead to transcriptional suppression of transition protein 1 (TNP1) and protamine 1 (PRM1) genes and the occurrence of infertility in animal models." (PMID 39876905, 2024). "Without the function of KDM3A in round spermatids, excessive methylation would lead to the transcription suppression of TNP1/PRM1 genes and the occurrence of infertility in animal models." (PMID 33349804, 2020). "The impaired function of oxidative phosphorylation could be the predominant reason for crossbred bull infertility; and significant downregulation of ZNF706, CRISP2, TNP2, and TNP1 genes indicates that they could serve as potential biomarkers for fertility in crossbred bulls." (PMID 34041237, 2021). "Consequently, the lack of TNP1 and PRM1 genes expression leads to the loss of the required condensation of chromosomes for proper packing in the sperm head, and it is considered as one of the causes of infertility in NOA men." (PMID 33349804, 2020). "The lack of TNP1 and TNP2 leads to defects in sperm head, reduced sperm motility, and infertility." (PMID 34041237, 2021).
male infertility (9 papers, 2015 to 2023). The inability of the male to effect fertilization of an ovum after a specified period of unprotected intercourse. "Although a distinct pathway has not been found yet, the reduced transcription of postmeiotic genes, including Tnp1, Tnp2, Prm1 and Prm2, in Brwd1-defective testes has been suggested to cause male infertility." (PMID 34473250, 2021). "At a false discovery rate (FDR) of 5%, we identified one significant whole blood DNA methylation change linked to conception via IVF, which was located ~3 kb upstream of TNP1, a gene previously linked to male infertility." (PMID 28340599, 2017). "TNP1 is a spermatid specific protein that is involved in the replacement of histones by protamines in the sperm chromatin and defects in this gene have been shown to cause male infertility." (PMID 33292187, 2020). "Thus far, only a few studies have analyzed the correlation between PRM1/2 and TNP1 polymorphisms and particular phenotypes of male infertility." (PMID 28977892, 2017). "This means that the deletion reduces TNP1 expression and may cause male infertility." (PMID 35207567, 2022). "Therefore, in the present study, we further investigated the association of some potentially functional PRM SNPs (rs2301365, rs737008, rs35576928, rs1646022 and rs2070923) and TNP1 (rs62189545) with the risk of male infertility in a large scale study of a Chinese population." (PMID 28977892, 2017). "We observed differential expression of a number of transcripts, such as PRM1, SPATA18, TNP1, EIF4G2, CANX, RANBP9, TCP11, which have previously been associated with male infertility." (PMID 25973848, 2015). "This section will briefly highlight the role of the eight (TNP1, TNP2, PDHA2, LDHC, SPINK2, ODF1, ODF2, and PCDHB3) common DEGs in male infertility as obtained from our findings." (PMID 35207567, 2022). "Consequently, downstream genes which are controlled by KDM3A such as PRM1 and TNP1 are not expressed and all these together drive to male infertility in NOA men." (PMID 33349804, 2020).
breast carcinoma (5 papers, 2011 to 2021). "Furthermore, rs4491709 is in LD with rs13387042 (r2 = 0.34 in the DNBC I study group), which is associated with breast cancer; the closest gene is TNP1 (160 kb telomeric)." (PMID 21931568, 2011). "The remaining four have all been studied for their effects in the development and maintenance of human breast cancers (TNP1, FST, ANKRD40, TRH)." (PMID 33957863, 2021). "To gain a preliminary indication on whether TNP-1 would induce cytoprotective autophagy in patient-derived tumors, we isolated primary cancer cells from the freshly excised tissues of a breast cancer and a gastric cancer patient." (PMID 30315154, 2018). "TNP-1, but not TNP-2, induced apparent autophagy in the cells derived from the breast cancer patient." (PMID 30315154, 2018).
Azoospermia (4 papers, 2020 to 2023). Absence of any measurable level of sperm,whereby spermatozoa cannot be observed even after centrifugation of the semen pellet. "TXNDC2 (effect size = − 4.25, FDR = 1.44E−15), PRM1 (effect size = − 5.37, FDR = 1.99E−10), PRM2 (effect size = − 5.16, FDR = 3.60E−10), and TNP1 (effect size = − 7.05, FDR = 6.48E−16) were all downregulated in the idiopathic azoospermia dataset." (PMID 34158577, 2021). "The results of that research showed that the expression of all the studied genes including KDM3A, TNP1, and PRM1 in all histological groups of azoospermia men with the tissue pattern of SCOC suggested a significant difference in the expression of hypospermatogenesis." (PMID 33349804, 2020).
autoimmune disease (1 paper, 2015). A disorder resulting from loss of function or tissue destruction of an organ or multiple organs, arising from humoral or cellular immune responses of the individual to their own tissue constituents. "C57BL/6 mice are not prone to autoimmune disease, but after 7–9 injections with RRP8 or TNP1, they demonstrated proteinuria." (PMID 26098692, 2015).
COVID-19 (1 paper, 2022). A disease caused by infection with severe acute respiratory syndrome coronavirus 2. "At the same time, the expression of the classical marker genes TNP1, PRM1 and PRM2 of sperm were reduced in COVID-19." (PMID 36685935, 2022).
gastric cancer (1 paper, 2018). A primary or metastatic malignant neoplasm involving the stomach. "In comparison, TNP-1 induced marginal autophagy in the cells derived from the gastric cancer patient, with CQ and 3-MA showing much reduced but still significant enhancement on TNP-1-mediated photothermal cell killing." (PMID 30315154, 2018).
glomerulonephritis (1 paper, 2015). A renal disorder characterized by damage in the glomeruli. "IC-deposited glomerulonephritis was induced in C56BL/6 mice by repeated stimulation with recombinant human RRP8 or TNP1 protein." (PMID 26098692, 2015). "Next, we examined whether IC would be formed by injection of human RRP8 or TNP1 into C57BL/6 mice and whether glomerulonephritis would occur predominantly when IC was formed with RRP8 or TNP1." (PMID 26098692, 2015). "Therefore, we planned to investigate whether glomerulonephritis would be induced by injecting recombinant mouse RRP8 or mouse TNP1 protein into mice." (PMID 26098692, 2015). "Therefore, we examined whether IC would be formed by injection of human RRP8 or TNP1 into C57BL/6 mice and whether glomerulonephritis would occur predominantly as a result of IC formation with RRP8 or TNP1." (PMID 26098692, 2015).
nephritis (1 paper, 2015). Inflammation of renal tissue. "Both anti-RRP8 and anti-TNP1 autoantibodies were detected in the sera of MRL/lpr mice that developed nephritis, closely resembling the pattern seen in human LN." (PMID 26098692, 2015). "The frequency of anti-TNP1 antibody was significantly higher in the SLE patients with nephritis than in those without nephritis (45.5% (n = 5) vs 9.4% (n = 6), respectively; p = 0.002, odds ratio 8.06, 95% confidence interval 1.8–34.5)." (PMID 26098692, 2015). "In addition, the positivity rates for both anti-RRP8 and anti-TNP1 autoantibodies were significantly higher in the LN group than in the SLE group without nephritis." (PMID 26098692, 2015). "Among SLE patients, 63.6% and 45.5% of those with LN were positive for anti-RRP8 and anti-TNP1 antibodies, compared with 12.5% and 9.4% of SLE patients without nephritis, respectively." (PMID 26098692, 2015).
ovarian tumors (1 paper, 2012). "Despite no expression of the TNP1 gene (KP-OVA-35) in ovarian tumors and several cancer cell lines, TNP1 demonstrated a high percent reactivity (30%)." (PMID 22684412, 2012).
rheumatic diseases (1 paper, 2015). "We compared the circulating levels of anti-RRP8 and anti-TNP1 antibodies among patients with rheumatic diseases using ELISA." (PMID 26098692, 2015). "ELISA analysis of sera from patients with various rheumatic diseases demonstrated reactivity for RRP8 and TNP1 in 20% and 14.7% of SLE patients, respectively, whereas there was little or no reactivity in patients with other rheumatic diseases." (PMID 26098692, 2015).
vasculitis (1 paper, 2015). "On the other hand, inflammatory changes such as vasculitis and infiltrating inflammatory cells were hardly observed in the lung, liver and spleen of both RRP8-injected and TNP1-injected mice." (PMID 26098692, 2015).
cancer (3 papers, 2012 to 2025). A tumor composed of atypical neoplastic, often pleomorphic cells that invade other tissues. "Furthermore, we demonstrated that autophagy induced by TNP-1 was pro-survival, as inhibition of autophagy enhanced cancer cell killing elicited by TNP-1." (PMID 30315154, 2018). "Two of these differentially expressed antigens (KP-OVA-38/C10orf62 and KP-OVA-52/C15orf60) are novel gene products, and the remaining tissue-restricted antigen (KP-OVA-35/TNP1) has not been previously studied in relation to cancer." (PMID 22684412, 2012). "Similar to CQ, 3-MA further enhanced the anti-cancer efficacy for TNP-1- but not TNP-2-mediated PTT, as the tumor weight of the TNP-1 + NIR + 3-MA group decreased by 91% compared to the PBS + NIR group, while the corresponding number was only 67% for the TNP-2 + NIR + 3-MA group." (PMID 30315154, 2018).
tumor (2 papers, 2018 to 2025). "Upon targeting tumor cells, TNP1/ZnPc was effectively endocytosed and predominantly passing through the lysosomes." (PMID 39776796, 2025). "Herein, we present a novel and general strategy for the construction of tumor-targeted activatable nanophotosensitizers (TNP1/PSs)." (PMID 39776796, 2025). "Within tumor lysosomes, the hydrolysis of the ester bonds and carbamates in TNP1/ZnPc results in the degradation of the cationic polymers." (PMID 39776796, 2025). "Upon targeting tumor cells, TNP1/PSs were effectively endocytosed and predominantly traversed the lysosomes, where degradation of the cationic polymer occurs, resulting in the spontaneous switch-on of PDT activity." (PMID 39776796, 2025). "Additionally, we thoroughly evaluated the cytotoxicity, tumor-targeted ability, and anti-tumor efficacy of TNP1/PSs in the 4T1 cell line." (PMID 39776796, 2025). "Crucially, benefitting from the full OFF of the nanophotosensitizer in the bloodstream prior to its entry into tumor cells, the intravenous administration of TNP1/ZnPc does not cause noticeable skin phototoxicity or any other adverse side effects even when exposed to simulated sunlight." (PMID 39776796, 2025). "PTT treatment mediated by TNP-1 significantly inhibited tumor growth, with CQ but not Dox further reducing the tumor volume under the TNP-1-mediated PTT." (PMID 30315154, 2018).
TNP1 also shares sentences with these, for which no sentence is quoted: oligospermia (2 papers); asthenospermia (1); colorectal cancer (1); ovarian carcinoma (1); Sertoli Cell-Only Syndrome (1); varicocele (1).